UCP2 (uncoupling protein 2)
Description:
Antiporter that exports dicarboxylate intermediates of the Krebs cycle in exchange for phosphate plus a proton across the inner membrane of mitochondria, a process driven by mitochondrial motive force with an overall impact on glycolysis, glutaminolysis and glutathione-dependent redox balance. Continuous export of oxaloacetate and related four-carbon dicarboxylates from mitochondrial matrix into the cytosol negatively regulates the oxidation of acetyl-CoA substrates via the Krebs cycle, lowering the ATP/ADP ratio and reactive oxygen species (ROS) production. May mediate inducible proton entry into the mitochondrial matrix affecting ATP turnover as a protection mechanism against oxidative stress. The proton currents are most likely associated with fatty acid flipping across the inner membrane of mitochondria in a metabolic process regulated by free fatty acids and purine nucleotides (By similarity). Regulates the use of glucose as a source of energy. Required for glucose-induced DRP1-dependent mitochondrial fission and neuron activation in the ventromedial nucleus of the hypothalamus (VMH). This mitochondrial adaptation mechanism modulates the VMH pool of glucose-excited neurons with an impact on systemic glucose homeostasis (By similarity). Regulates ROS levels and metabolic reprogramming of macrophages during the resolution phase of inflammation. Attenuates ROS production in response to IL33 to preserve the integrity of the Krebs cycle required for persistent production of itaconate and subsequent GATA3-dependent differentiation of inflammation-resolving alternatively activated macrophages (By similarity). Can unidirectionally transport anions including L-malate, L-aspartate, phosphate and chloride ions. Does not mediate adaptive thermogenesis (By similarity).
Synonyms: SLC25A8; BMIQ4; UCPH
Tractability: Antibody: UniProt predicts a signal peptide or a membrane-spanning region.
Gene: Protein-coding gene on chromosome 11 (73,974,061 to 73,983,542, reverse strand). Ensembl gene ENSG00000175567.
Subcellular location: Mitochondrion inner membrane
Subcellular location (Human Protein Atlas): Mitochondria
Pathways (Reactome):
Metabolism: The fatty acid cycling model
Gene Ontology:
Molecular function: antiporter activity; chloride transmembrane transporter activity; L-aspartate transmembrane transporter activity; malate transmembrane transporter activity; oxaloacetate transmembrane transporter activity; phosphate ion uniporter activity; protein binding; protein homodimerization activity; proton transmembrane transporter activity; secondary active sulfate transmembrane transporter activity; long-chain fatty acid transmembrane transporter activity; GDP binding
Biological process: C4-dicarboxylate transport; glutamine metabolic process; glycolytic process; mitochondrial transmembrane transport; negative regulation of calcium import into the mitochondrion; response to hypoxia; adaptive thermogenesis; cellular response to glucose stimulus; macrophage differentiation; mitochondrial fission; positive regulation of cold-induced thermogenesis; proton transmembrane transport; reactive oxygen species metabolic process; response to cold; cellular response to amino acid starvation; cellular response to hormone stimulus; cellular response to insulin stimulus; cellular response to lead ion; chloride transmembrane transport; L-aspartate transmembrane transport; liver regeneration; long-chain fatty acid transport; malate transmembrane transport; mitochondrial transport; negative regulation of apoptotic process; and 9 more
Cellular component: mitochondrion; mitochondrial inner membrane; mitochondrial membrane
Genetic constraint (gnomAD): Loss-of-function variants: 28 observed, 34.06 expected, observed/expected ratio (o/e) 0.82, 90% interval 0.61 to 1.13. The upper end of that interval is the gene's LOEUF score, 1.13, which puts it in group 4 of 6, group 1 being the genes least tolerant of losing a copy. Missense variants: 377 observed, 430.78 expected, observed/expected ratio (o/e) 0.88, 90% interval 0.8 to 0.95. Synonymous variants: 142 observed, 165.99 expected, observed/expected ratio (o/e) 0.86, 90% interval 0.75 to 0.98.
Homologues: Orthologues: chimpanzee UCP2 (99% identical), macaque UCP2 (98% identical), dog UCP2 (97% identical), mouse Ucp2 (96% identical), guinea pig UCP2 (96% identical), rabbit UCP2 (95% identical), rat Ucp2 (94% identical), pig UCP2 (90% identical), tropical clawed frog ucp2 (81% identical), zebrafish ucp2 (81% identical). Paralogues in human: UCP3 (72% identical), UCP1 (57% identical), SLC25A14 (36% identical), SLC25A30 (36% identical), SLC25A27 (33% identical), SLC25A12 (31% identical), SLC25A13 (30% identical), SLC25A1 (29% identical), SLC25A34 (28% identical), SLC25A10 (27% identical), SLC25A21 (26% identical), SLC25A16 (25% identical), and 37 more.
Diseases named in the same sentence as UCP2 in open-access papers:
UCP2 is named in the same sentence as 251 diseases in open-access papers, as found by Europe PMC text mining. Sharing a sentence is not in itself a finding about the gene and the disease. The quoted sentences say what the papers report.
Obesity (176 papers, 2006 to 2025). Accumulation of substantial excess body fat. "In summary, this study highlighted the pivotal role of the oncogenic FABP4/UCP2 axis and its association with unfavourable treatment outcomes, particularly in the context of obesity-related CRC." (PMID 39823981, 2025). "Specifically, individuals homozygous for the Val allele of UCP2 Ala55Val exhibited reduced mitochondrial uncoupling, increased metabolic rate, and a higher risk for obesity and T2D." (PMID 41300761, 2025). "UCP2, a critical player in lipid and energy metabolism, is associated with obesity and hyperinsulinemia." (PMID 37570835, 2023). "Variants of UCP2 that cause reduced protein expression and/or activity in humans is associated with obesity depending upon ethnicity and sex and lower energy expenditure." (PMID 37561578, 2023). "For example, UCP2 upregulation in islets of ob/ob mice caused reduced ATP synthesis and attenuated insulin release, ultimately developing obesity and type 2 diabetes mellitus." (PMID 36266633, 2022). "The role of UCP2 in insulin secretion has also been recently reviewed, describing studies linking UCP2 to obesity that focus on the inflammatory process associated with ROS." (PMID 35884932, 2022). "The common G allele was associated by both in vivo and in vitro evidence with a reduction of UCP2 mRNA expression, increased ROS production, increased risk of obesity, and, at the same time, reduced risk of T2DM." (PMID 35629388, 2022). "The UCP2 protein is encoded by a gene mapping on human chromosome 11, in a region linked to energy homeostasis and obesity." (PMID 35629388, 2022). "At present, most previous studies have found that two common polymorphisms of UCP2 gene including rs659366 (located in the promoter region) and rs660339 (a missense variant in exon 4) were closely associated with obesity and diabetes." (PMID 33888769, 2021). "Overall, these results seem to indicate that obesity-dependent induction of UCP2 in pancreatic β-cells has a pathogenic effect towards the development of insulin resistance and in turn diabetes mellitus." (PMID 34829617, 2021). "Previous study revealed that the A allele of the UCP2-866G/A polymorphism contributes to insulin resistance and obesity when compared with G allele." (PMID 34712730, 2021). "A reduced UCP2 expression and activity has been linked to obesity-associated metabolic disorders, such as T2DM, hypertension and atherosclerosis." (PMID 32772323, 2021). "Various studies have presented UCP-2 45-bp D/I polymorphism association with a higher degree of obesity, insulin resistance, dyslipidemia, and lower adjusted metabolic rate." (PMID 33957975, 2021). "Several studies in different populations have verified that carriers of the I-allele of the UCP-2 gene had a significantly higher BMI and the possibility of obesity." (PMID 33957975, 2021). "Because Ucp2 is widely expressed in various tissue types, association of its polymorphisms are not limited to obesity and diabetes." (PMID 32450815, 2020). "UCP2 gene variants were found to be associated with reduced insulin sensitivity and obesity, metabolic syndrome, prediabetes and type 2 diabetes mellitus, hypertension, coronary artery disease, and stroke outcome." (PMID 32560241, 2020). "The T allele has been associated with higher UCP2 expression and energy expenditure, lower risk of obesity, and lower Homeostatic Model Assessment (HOMA) index." (PMID 32858880, 2020). "The most contributing SNP to this consortium was rs1801253-ADRB1, as well as other obesity risk-associated SNPs (UCP2, ADIPOQ, LEP, MC4R, etc.)." (PMID 32398726, 2020). "Ins allele carriers had higher BMI values, which increased the risk of obesity when the genome contained the Ins allele of Ucp2." (PMID 32450815, 2020). "As a consequence, UCP2 gene expression has been associated with obesity, and this has been confirmed in humans and animals." (PMID 30719347, 2019).
Obesity (continued). "The UCP2 gene is located on chromosome 7 of the mouse and chromosome 11 (11q13) of humans, near a region linked to diabetes and obesity." (PMID 29351723, 2018). "Both UCP2 and overweight/obesity are associated with insulin resistance, a fundamental aspect of the etiology of T2DM." (PMID 29529994, 2018). "In thisphenomenon participate the uncoupling proteins (UCPs) and in consequence, the genesthat encode these molecules (UCP1, UCP2 andUCP3) are regarded as candidate genes for obesity, T2DM andcardiovascular disease." (PMID 29786102, 2018). "The association of the polymorphisms in UCP2 with diabetes and obesity have been widely evaluated, most studies focused on Ala55Val (rs660339) in exon 4, 45 bp insertion/deletion in exon 8, and -866G/A (rs659336) in the promoter region." (PMID 29849618, 2018). "The ucp2 Ala55Val polymorphism is associated with a lower degree of uncoupling, lower energy expenditure, and, in turn, with a higher risk of obesity or higher incidence of diabetes." (PMID 29351723, 2018). "In order to test the association between UCP2 gene polymorphism and obesity, subjects were divided into 2 groups: AA + GA and GG genotype." (PMID 28686191, 2017). "The interaction between UCP2 gene polymorphism, dietary intake and obesity was also seen in our previous studies." (PMID 28686191, 2017). "Genetic variants in the UCP2/UCP3 cluster have been considered candidate markers for obesity, diabetes, and fat metabolism in humans." (PMID 28615046, 2017). "UCP2 is a protein that involved in energy metabolism and the polymorphism of this gene was associated with obesity." (PMID 28686191, 2017). "In a similar manner, the Ala55Val polymorphism (rs660339) of UCP2 gene was associated with severe forms of obesity in a Han Chinese population." (PMID 29317790, 2017). "UCP-2 overexpression leads to decreased mitochondrial membrane potential and to ATP depletion, associated with obesity-induced fatty liver." (PMID 27359329, 2016). "The relationship of −866G>A gene polymorphism of UCP2 (rs659366) with obesity and type 2 diabetes has been reported previously." (PMID 27301474, 2016). "Our data corroborate previous findings in humans showing that obesity, low rates of energy expenditure and metabolic complications are linked to certain UCP2 polymorphisms, such as the presence of 3′UTR Ins variant altering mRNA processing or stability." (PMID 25622596, 2015). "Though, in some studies, the I-allele of UCP-2 has been found to be associated with development of obesity." (PMID 24398006, 2014). "In this regard, several UCP-2 gene polymorphisms were linked to an increased body weight index or obesity in Pima Indians and in Balinese population or with insulin resistance or T2DM." (PMID 25077985, 2014). "In agreement with our data, they reported an association between the UCP2-866A allele and protection for obesity in Europeans." (PMID 24804925, 2014). "We did not detect association between any variants in the ADRB2 and UCP2 genes and obesity phenotypes." (PMID 24879436, 2014). "The association between the UCP2 -866G/A polymorphism and obesity was investigated in 12 studies with a total of 7,390 cases and 9,860 controls." (PMID 23560041, 2013). "Recently, numerous studies have examined the associations between the three common variants in the UCP2-UCP3 gene cluster and diabetes or obesity risk, including UCP2 -866 G/A, Ala55Val C/T and UCP3 -55 C/T polymorphism." (PMID 23560041, 2013). "Twelve studies examined the association between the UCP2 -866G/A polymorphism and obesity risk, nine studies for the UCP2 Ala55Val polymorphism and eight for the UCP3 -55C/T polymorphism." (PMID 23560041, 2013). "Characteristics of the UCP2 Ala55Val polymorphism allelic and genotype distribution for obesity risk in studies included in the meta-analysis." (PMID 23560041, 2013). "Characteristics of the UCP2 -866G/A polymorphism allelic and genotype distribution for obesity risk in studies included in the meta-analysis." (PMID 23560041, 2013).
Obesity (continued). "Obesity and chronic hyperglycemia increase mitochondrial superoxide (O2•−) production, and this causes activation of UCP2 and results in pancreatic islet β-cell dysfunction." (PMID 22110477, 2012). "We have demonstrated the importance of environmental settings in studying the influence of the common UCP2 gene polymorphisms in the development of obesity in a Balinese population." (PMID 22533685, 2012). "We examined the association of commonly observed UCP2 G(−866)A (rs659366) and Ala55Val (C > T) (rs660339) single nucleotide polymorphisms (SNPs) with obesity, high fasting plasma glucose, and serum lipids in a Balinese population." (PMID 22533685, 2012). "In the present study of the Balinese population, we examined the association of two commonly observed UCP2 gene polymorphisms, the G(−866)A in the promoter region (rs659366) and the Ala55Val in exon 4 (rs660339), with obesity, high FPG and high serum lipids." (PMID 22533685, 2012). "We demonstrated that the UCP2 gene polymorphisms G(−866)A and Ala55Val are associated with obesity in Balinese, but only if the urban environment was taken into account." (PMID 22533685, 2012). "UCP2, a well-known inner mitochondrial membrane protein, responsible for energy dissipation and heat production, has been found to associate with obesity, diabetes and regulation of insulin secretion." (PMID 22369239, 2012). "Uncoupling protein 2 (UCP2) gene polymorphisms have been reported as genetic risk factors for obesity and type 2 diabetes mellitus (T2DM)." (PMID 22533685, 2012). "In this study, we aim to examine the association of the UCP2 gene G(−866)A and Ala55Val SNPs with obesity, high FPG and serum lipids in a Balinese population, which has not been characterized for the SNPs, comparing the urban and rural population." (PMID 22533685, 2012). "Our study has provided compelling evidence regarding the importance of environmental settings in studying the involvement of UCP2 gene polymorphisms in the development of obesity in a Balinese population." (PMID 22533685, 2012). "Instead, UCP2 has been implicated in free radical scavenging relevant to diverse physiological and pathological processes, including obesity, neurodegenerative diseases, ageing and cancer." (PMID 21712825, 2011). "These include associations between UCP2 G866A and A55V and glucose-induced insulin secretion, as well as obesity and metabolism." (PMID 17397545, 2007). "Population studies showed that a common polymorphism in the UCP2 promoter, -866G/A, was associated with a reduced risk of obesity in Caucasian Europeans." (PMID 16968550, 2006). "Also, increased expression of UCP1 and UCP2 genes, both of which are associated with obesity, indicates an obesity threat." (PMID 40024983, 2025). "The SIRT1-Ppargc1a-Ucp2 pathway is associated with insulin resistance and obesity." (PMID 39707176, 2024). "UCP2 is associated with metabolic disorders such as diabetes, obesity, and cardiovascular disease." (PMID 36978905, 2023). "The gene localization in chromosomal regions linked to hyperinsulinaemia and obesity suggested that UCP2 could play a role in the control of energy balance and, in addition, in the response to inflammatory stimuli." (PMID 37175829, 2023). "UCP2 expression variants were found to be associated with insulin sensitivity and diabetes mellitus, obesity and metabolic syndrome, cardiac diseases, immunity process, tumorigenesis and cancer, aging, and neurological diseases." (PMID 33746782, 2021). "UCP2 G-866A has been linked to a predisposition to diabetes, obesity, and inflammation." (PMID 34527175, 2021). "The Ucp1 homologues, such as Ucp2 and Ucp3 also deserve attention among candidate genes whose polymorphisms may be associated with obesity and risk factors for cardiovascular diseases." (PMID 32450815, 2020).